AQP11 (aquaporin 11)
Description:
Channel protein that facilitates the transport of water, glycerol and hydrogen peroxide across membrane of cell or organelles guaranteeing intracellular homeostasis in several organes like liver, kidney and brain. In situation of stress, participates in endoplasmic reticulum (ER) homeostasis by regulating redox homeostasis through the transport of hydrogen peroxide across the endoplasmic reticulum membrane thereby regulating the oxidative stress through the NADPH oxidase 2 pathway. Plays a role by maintaining an environment suitable for translation or protein foldings in the ER lumen namely by participating in the PKD1 glycosylation processing resulting in regulation of PKD1 membrane trafficking thereby preventing the accumulation of unfolding protein in ER (By similarity). Plays a role in the proximal tubule function by regulating its endosomal acidification (By similarity). May play a role in postnatal kidney development (By similarity).
Synonyms: AQPX1
Tractability: Antibody: its Gene Ontology location is reachable by antibodies, with high confidence; UniProt places it where antibodies can reach, with medium confidence; UniProt predicts a signal peptide or a membrane-spanning region; the Human Protein Atlas places it where antibodies can reach. PROTAC: its protein half-life has been measured.
Gene: Protein-coding gene on chromosome 11 (77,589,391 to 77,611,064, forward strand). Ensembl gene ENSG00000178301.
Subcellular location: Endoplasmic reticulum membrane; Cytoplasmic vesicle membrane; Cell membrane
Subcellular location (Human Protein Atlas): Plasma membrane; Vesicles
Pathways (Reactome):
Transport of small molecules: Passive transport by Aquaporins
Gene Ontology:
Molecular function: glycerol channel activity; hydrogen peroxide channel activity; water channel activity; channel activity
Biological process: glycerol transmembrane transport; hydrogen peroxide transmembrane transport; intracellular water homeostasis; monoatomic ion transport; positive regulation of cell population proliferation; protein homooligomerization; urea transport; water transport; glycoprotein biosynthetic process; negative regulation of epithelial cell proliferation; negative regulation of ERAD pathway; negative regulation of response to endoplasmic reticulum stress; protein targeting to membrane; proximal tubule development; intracellular oxygen homeostasis; transmembrane transport
Cellular component: cell surface; cytoplasmic vesicle membrane; endoplasmic reticulum; endoplasmic reticulum membrane; plasma membrane; cytoplasm; membrane
Genetic constraint (gnomAD): Loss-of-function variants: 15 observed, 12.86 expected, observed/expected ratio (o/e) 1.17, 90% interval 0.78 to 1.74. The upper end of that interval is the gene's LOEUF score, 1.74, which puts it in group 6 of 6, group 1 being the genes least tolerant of losing a copy. Missense variants: 324 observed, 312.54 expected, observed/expected ratio (o/e) 1.04, 90% interval 0.95 to 1.14. Synonymous variants: 158 observed, 132.96 expected, observed/expected ratio (o/e) 1.19, 90% interval 1.04 to 1.36.
Homologues: Orthologues: chimpanzee AQP11 (99% identical), macaque AQP11 (98% identical), pig AQP11 (85% identical), rabbit AQP11 (85% identical), dog AQP11 (85% identical), mouse Aqp11 (83% identical), guinea pig AQP11 (80% identical), rat Aqp11 (76% identical), zebrafish aqp11 (35% identical), tropical clawed frog aqp11 (34% identical), Drosophila melanogaster AQP (22% identical), Caenorhabditis elegans aqp-9 (20% identical), and 2 more. Paralogues in human: AQP12B (28% identical), AQP12A (27% identical).
Diseases named in the same sentence as AQP11 in open-access papers:
AQP11 is named in the same sentence as 50 diseases in open-access papers, as found by Europe PMC text mining. Sharing a sentence is not in itself a finding about the gene and the disease. The quoted sentences say what the papers report.
renal failure (7 papers, 2012 to 2025). "At the same time, studies had shown that the afunction of AQP11 was associated with acute kidney injury and diabetic nephropathy." (PMID 35245343, 2022). "Studies using AQP11-deficient mice have shown an abnormal swelling of epithelial cells in kidneys, leading to cyst formation in proximal tubes and eventually renal failure and death." (PMID 22731103, 2012). "When the expression deletion of AQP11 occurs, it can lead to the formation of proximal tubule cysts in the kidney caused by PC1 transport defects, which in turn leads to polycystic kidney disease and induces severe renal failure." (PMID 35245343, 2022). "AQP11 knockout mice die early because of renal failure and retarded growth." (PMID 27107718, 2016). "As the progressive nature of renal failure in AQP11(−/−) mice suggests, the cyst epithelium may still need AQP11 and enhanced autophagy will be helpful for its survival." (PMID 27916883, 2016).
breast carcinoma (6 papers, 2020 to 2023). "AQP11 transcripts, at high levels, have been associated with poor survival in lung adenocarcinoma but, conversely, better survival in breast cancer, suggesting cancer-specific contributions of different classes of aquaporins." (PMID 37760476, 2023). "al. suggested that increased AQP11 is correlated with better prognosis in colorectal and breast cancer patients." (PMID 37175840, 2023). "Unexpectedly, increased AQP7 and AQP8 levels were associated with better survival times in glioma, ovarian and endometrial cancers, and increased AQP11 with better survival in colorectal and breast cancers." (PMID 32679804, 2020). "A previous study performing transcriptomic analyses on breast cancer biopsies revealed increased mRNA expression of AQP1, AQP3, AQP5, AQP7, AQP9 and AQP11 when compared to overall median AQP levels in the biopsies." (PMID 37681917, 2023). "Transcriptomic analyses using the Human Protein Atlas database revealed higher mRNA levels of several AQPs in human breast cancer, namely AQP1, AQP3, AQP5, AQP7, AQP9 and AQP11, when compared to overall median AQP expression levels in the biopsies." (PMID 37681917, 2023).
polycystic kidneys (6 papers, 2016 to 2023). "AQP11 is expressed in kidney, liver, testes, brain, and fat, and AQP11 knockout mice die 1 month after birth with polycystic kidneys, possibly caused by ER dysfunction." (PMID 34973181, 2022). "Although AQP11 is widely expressed, limited abnormalities were observed in AQP11-deficient mice: intracellular vacuoles in the kidney, liver, and intestine and polycystic kidneys." (PMID 27258268, 2016). "Disruption of the Aqp11 gene in mice leads to intracellular vacuolization of periportal hepatocytes and a severe form of polycystic kidney disease (PKD) with uremic death before weaning due to renal failure." (PMID 37681902, 2023). "It was ascertained that AQP11-knockout mice develop polycystic kidney disease and die prematurely, suggesting the importance of AQP11 in intravesicular homeostasis." (PMID 29194396, 2017). "The purpose of this study was to examine the autophagy activity in the AQP11(−/−) kidney in the process of developing polycystic kidneys to document the role of autophagy in cell survival." (PMID 27916883, 2016). "Further studies are needed to assess whether the PKD provoked by the depletion of Aqp11 in mice triggers the same liver cysts induced by the autosomal recessive form of PKD, a well-known form of PKD caused by homologous congenital polycystic kidney." (PMID 37681902, 2023). "On the other hand, the antibody used in the rat study has not stained the kidney, thus suggesting a poor sensitivity or specificity of the antibody, as the AQP11 mRNA expression in the kidney is relatively high and its absence produces proximal tubular polycystic kidneys." (PMID 27258268, 2016). "Thus, the induction of autophagy will be necessary for the damaged vacuolated cells in the AQP11(−/−) kidney to survive even though they are transformed to cyst epithelia of polycystic kidneys." (PMID 27916883, 2016). "While AQP11-deficient mice have developed fatal polycystic kidneys at one month old, the role of AQP11 in the brain was not well appreciated." (PMID 27258268, 2016).
intracerebral hemorrhage (4 papers, 2022 to 2025). A cerebrovascular disorder characterized by bleeding into one or both cerebral hemispheres including the basal ganglia and the cerebral cortex. "MiR-27a-3p participates in complications such as neuronal loss and neurological function impairment after intracerebral hemorrhage by targeting AQP11." (PMID 40682202, 2025). "Indeed, Xi demonstrated that Aqp11 was up-regulated following intracerebral hemorrhage (ICH), which was accompanied with increased BBB permeability and development of brain edema." (PMID 36009321, 2022). "One study has shown that miRNA-27a-3p mimics target the membrane protein, Aquaporin-11 (AQP11), located in the endothelial cells of brain capillaries, and has protective effects on BBB integrity in rats with intracerebral hemorrhage." (PMID 36009578, 2022).
chronic kidney disease (3 papers, 2019 to 2024). Impairment of the renal function secondary to chronic kidney damage persisting for three or more months. "A community-based cohort study involving 620 participants with chronic kidney disease (CKD) firstly revealed that AQP11 rs2276415 variant is associated with CKD progression." (PMID 30654539, 2019). "Although no pathological conditions have been correlated with altered AQP11 in humans, AQP11 rs2276415 variation was characterized as a genetic factor of predisposition to develop kidney diseases such as chronic kidney disease, transplantation failure, or type 2 diabetes." (PMID 39125952, 2024).
cyst (3 papers, 2012 to 2016). A sac-like closed membranous structure that may be empty or contain fluid or amorphous material. "As PC-1 is a gene product responsible for autosomal dominant polycystic kidney disease (ADPKD), cyst formation in AQP11-null (AQP11(−/−)) mice may be caused by defective PC-1 trafficking which is limited to the proximal tubule." (PMID 27916883, 2016). "Using green fluorescent protein (GFP)-LC3 transgenic mice and AQP11(−/−) mice, we found that the number of GFP-LC3–positive puncta was increased in the proximal tubule of AQP11(−/−) mice before the cyst formation." (PMID 27916883, 2016). "To monitor autophagy in vivo, we introduced GFP-LC3 as a marker for autophagy in AQP11(−/−) mice and found enhanced autophagy activity throughout the development of the proximal tubule from vacuolated cells to cyst epithelia." (PMID 27916883, 2016). "Here we reported that autophagy was enhanced in the kidney of AQP11(−/−) mice before and even after cyst formation." (PMID 27916883, 2016). "As the intracellular vacuoles are formed at the age of one to two weeks and subsequently the cysts develop at three to four weeks, the results indicated enhanced autophagy activity before and after the cyst formation in the kidney of AQP11(−/−) mice." (PMID 27916883, 2016). "As AQP11 is mostly expressed in the ER of proximal tubular cells, AQP11 may play an important role in the ER and its disruption may lead to cyst formation." (PMID 27916883, 2016). "Therefore, AQP11(−/−) mice had enhanced autophagy activity before and after cyst formation in agreement with the results of qRT-PCR." (PMID 27916883, 2016). "As the damaged proximal tubular cells with intracellular vacuoles form cysts later, we postulated that autophagy may play a role in the cyst formation and examined autophagy activity before and after cyst development in AQP11(−/−) kidneys." (PMID 27916883, 2016). "Thus, all the caspase genes examined were enhanced in the AQP11(−/−) kidney before (at two weeks) and after (at eight weeks) cyst formation with remarkably higher expressions of Casp1, Casp4 and Casp12." (PMID 27916883, 2016). "We observed cyst-like swellings in kidney sections from the HP group, indicating that significant downregulation of Aqp11 may play a role in cyst formation in rats fed a HP diet." (PMID 22235299, 2012). "As the proximal tubule suffers from extensive cell damage with intracellular vacuoles in the absence of AQP11 before cyst formation, higher autophagy activities will be necessary for the survival of these cells as previously reported in other kidney injury models." (PMID 27916883, 2016). "It is possible that the cyst epithelium may also suffer from a cellular damage in the absence of AQP11 with diminished glomerular filtration and narrowed vessels compressed by cysts, which eventually compromise the blood supply to cyst epithelia." (PMID 27916883, 2016).
adenocarcinoma of lung (2 papers, 2022 to 2023). "has suggested that high AQP11 expression can be associated with reduced overall survival among patients with lung adenocarcinoma." (PMID 35847914, 2022). "have demonstrated that high AQP11 mRNA expression is negatively prognostic in patients with adenocarcinoma of lung (LUAD)." (PMID 35847914, 2022). "The Cancer Genome Atlas (TCGA) database analysis of previously untreated lung adenocarcinoma detected 13% tumors with elevated AQP11 mRNA expression." (PMID 35847914, 2022).
brain edema (2 papers, 2016 to 2022). Increased intracellular or extracellular fluid in brain tissue. "Its restricted localization at the BBB and the down-regulation of AQP4 expression in AQP11-deficient brains suggest that AQP11 may play a role in the BBB water transport and in the pathophysiology of brain edema." (PMID 27258268, 2016). "For instance, the localization of Aqp11 in the epithelium supports that it is involved in the permeability of the blood-brain-barrier (BBB) and the pathophysiology of brain edema." (PMID 36009321, 2022).
edema (2 papers, 2016). An abnormal accumulation of fluid beneath the skin, or in one or more cavities of the body. "In fact, we are planning to study brain edema models in AQP11-deficient mice, which may lead to a new therapy against brain edema." (PMID 27258268, 2016). "Since AQP11 is also selectively expressed in brain endothelium that forms blood-brain barrier and is important for the prevention of brain edema, the expression pattern and function of this water channel seems to have distinct and important functions in the central nervous system." (PMID 27107718, 2016).
gastric cancer (2 papers, 2018 to 2022). A primary or metastatic malignant neoplasm involving the stomach. "AQP11 mRNA expression was associated with better OS in gastric cancer patients with surgery alone and other adjuvant chemotherapeutic treatment." (PMID 29678898, 2018). "We found that high expression of AQP9 and AQP11 mRNAs were associated with improved OS in male gastric cancer patients." (PMID 29678898, 2018). "However, the survival analysis demonstrated that AQP11 mRNA expression was significantly associated with improved OS in all gastric patients involving both intestinal and diffuse histological subtypes especially in advanced stage male gastric cancer patients." (PMID 29678898, 2018). "Abnormal expression of AQP10 and AQP11 was reported in gastric cancer, but the regulatory mechanism demanded prompt solution." (PMID 36254092, 2022). "Eventually, AQP11 mRNA high expression was significantly associated with stages III and IV gastric cancer patients." (PMID 29678898, 2018). "Furthermore, AQP8 and AQP11 mRNA expression in other adjuvant chemotherapy showed better OS in gastric cancer patients." (PMID 29678898, 2018). "Similarly, AQP5 protein had low expression in normal tissues, whereas AQP11 protein had higher expression in normal gastric tissues, but both proteins have medium expression in cytoplasm and membranous region of gastric cancer tissues." (PMID 29678898, 2018). "In which, we revealed AQP3, AQP9, and AQP11 mRNA expression were associated with improved OS in all gastric cancer patients especially with intestinal subtypes, whereas AQP0, AQP1, AQP4, AQP5, AQP6/2L AQP8, and AQP10 mRNA expression were associated with poor OS in all gastric cancer patients." (PMID 29678898, 2018). "Additionally, AQP9 and AQP11 mRNA expression with negative HER2 was associated with longer survival rate in gastric cancer patients." (PMID 29678898, 2018).
gastritis (2 papers, 2016 to 2023). Inflammation of the stomach. "Collectively, these results indicate that the expression of several subtypes of AQPs (AQP1, AQP3, AQP4, AQP5, AQP7 and AQP11) is upregulated by gastritis, and more studies are essential to investigate their potentials as diagnostic biomarkers and drug targets for gastritis therapy." (PMID 27589719, 2016).
Hydrocephalus (2 papers, 2022 to 2024). Hydrocephalus is an active distension of the ventricular system of the brain resulting from inadequate passage of CSF from its point of production within the cerebral ventricles to its point of absorption into the systemic circulation. "This work analyzes the expression of the four most abundant aquaporins (AQPs) (AQP1, AQP4, AQP9, and AQP11) in the brains of mice and discuss their contribution to hydrocephalus." (PMID 35454119, 2022).
lung carcinoma (2 papers, 2022 to 2023). "In lung cancer cell lines, AQP11 expression was positively correlated with cisplatin resistance and may be a predictor of cisplatin resistance in lung cancer." (PMID 38136293, 2023).
ovarian carcinoma (2 papers, 2018 to 2020). A malignant neoplasm originating from the surface ovarian epithelium. "Conversely, a fascinating observation was that higher levels of AQPs 7 and 8 were associated with lower hazard ratios in glioblastoma and ovarian cancer; and AQP11 appeared to have a beneficial influence in breast and colorectal cancers." (PMID 32679804, 2020). "Overexpression of AQP3, AQP6/2L, and AQP11 were associated with favorable OS in grade III ovarian cancer patients." (PMID 29472315, 2018). "High level of AQP11 mRNA was significantly associated with better OS for all ovarian cancer patients, HR = 0.78 (0.63–0.95), P=0.015 and serous ovarian cancer, HR = 0.7 (0.56–0.88), P=0.0021." (PMID 29472315, 2018). "In general, our results showed that the presence of AQP10 and AQP11 mRNA linked with positive outcomes in ovarian cancer patients." (PMID 29472315, 2018). "Our results revealed that higher AQP0, AQP1, and AQP4 mRNA expression were correlated with poor OS, whereas higher AQP3, AQP5, AQP6, AQP8, AQP10, and AQP11 showed better OS in ovarian cancer patients." (PMID 29472315, 2018). "In addition, we observed a better OS with higher AQP11 mRNA expression in all ovarian cancer patients mainly with serous subtypes, as well as in poorly differentiated (grade III) cancer patients." (PMID 29472315, 2018). "Intriguingly, when concurrent (Platin + Taxol) treatment and prognostic significance were analyzed, the data showed that high expression of AQP0 and AQP1 mRNA were correlated to decrease survival rate and high expression of AQP3, AQP6, and AQP11 were correlated to good OS in ovarian cancer patients." (PMID 29472315, 2018). "Additionally, AQP3, AQP6, and AQP11 mRNA expression were correlated with better OS, whereas AQP0 and AQP1 showed poor OS in all ovarian cancer patients treated with Platin, Taxol, and Taxol + Platin chemotherapy." (PMID 29472315, 2018).
type 2 diabetes (2 papers, 2020 to 2024). "Therefore, our hypothesis was that AQP11 is involved in the relationship between ER stress and chronic inflammation in the context of human obesity and obesity-associated type 2 diabetes (T2D)." (PMID 32512939, 2020). "Accordingly, our data showed that transcript and protein levels of AQP11 were higher in the subcutaneous adipose tissue of obese patients with type 2 diabetes than those found in individuals with normoglycemia." (PMID 32512939, 2020). "We found that obesity and obesity-associated type 2 diabetes increased (p < 0.05) AQP11 mRNA and protein in visceral adipose tissue, but not subcutaneous fat." (PMID 32512939, 2020).